CTTN (cortactin)
Diseases named in the same sentence as CTTN in open-access papers (continued):
Sharing a sentence is not in itself a finding about the gene and the disease.
colon carcinoma (16 papers, 2014 to 2024). "Infection of all three colon cancer cell lines with adenovirus encoding CTTN (Ad-CTTN) led to a significant increase in CTTN mRNA expression, which was especially prominent in HCT29 cells." (PMID 24465712, 2014). "The qPCR results for CTTN showed a statistically lower expression level in colon cancer samples compared to the normal samples, which is contrary to our TCGA database analysis." (PMID 39234565, 2024). "The expression levels of CD2AP, GRB2, WASL, and CAPZA1 are generally downregulated, while those of SRC and CTTN are upregulated in colon cancer samples compared with their levels in normal samples at the RNA and/or protein levels." (PMID 39234565, 2024). "Rac1 and CTTN play major roles in promoting epithelial tumor metastasis, and the activation of these two genes has been reported in ovarian, breast, and colon cancers." (PMID 37970440, 2023). "In support of these observations, it was shown that in colon cancer cells, curcumin-mediated activation of PTP1B led to cortactin dephosphorylation at Y-421, resulting in reduced cell motility in colon cancer." (PMID 31936446, 2020). "Although the role of the PTPN1/cortactin axis has been identified in the mechanism of CUR-induced inhibition of colon cancer cell migration, additional studies are required to establish the mechanism by which CUR activates PTPN1." (PMID 29743988, 2018). "In the current study, we used CBF as a surrogate marker for Chansu, and further determined the role of CBF in the modulation of cortactin expression in human colon cancer cells." (PMID 26134506, 2015). "Cortactin is overexpressed in colon cancer tissues and has been shown to be an important factor in tumour progression and cancer invasion." (PMID 26134506, 2015). "Several lines of evidence support our conclusions about the role of PTPN1/cortactin axis in the mechanism of curcumin-induced inhibition of colon cancer cell migration." (PMID 24465712, 2014). "We found that in colon cancer cells, cortactin interacts with CTNND1, and that curcumin strongly decreased this association, likely due to diminished cortactin phosphorylation at Tyr421." (PMID 24465712, 2014). "Since we observed significant increase in the levels of pTyr421-cortactin in the majority of the colon tumor samples analyzed, we examined the levels of pTyr421-cortactin in colon cancer cell lines following treatment with curcumin." (PMID 24465712, 2014). "Next, we examined 19 matched pairs of colon tumor specimens for cortactin protein expression by western blot." (PMID 24465712, 2014). "Moreover, it is already known that cortactin promotes colon cancer cell progression and mediates EMT." (PMID 37894817, 2023). "Similarly, the mRNA expression levels of CTTN was correlated to a larger tumor size in colon cancer and non-small cell lung cancers." (PMID 33407452, 2021). "However, we did not detect significant differences in protein expression in the other reported substrate for Hakai, Cortactin, during colon carcinoma development." (PMID 29472634, 2018). "CBF inhibits cortactin expression and nuclear translocation in colon cancer cells in vitro and in mouse models bearing human colon tumour in vivo, suggesting it might disrupt actin-regulated cell movement." (PMID 26134506, 2015). "In this study, we investigated cortactin expression in colon cancer." (PMID 24465712, 2014). "Moreover, overexpression of cortactin using adenoviral delivery in three colon cancer cell lines promoted cell migration, thus highlighting the role of cortactin in colon cancer cell motility." (PMID 24465712, 2014). "We also investigated cortactin phosphorylation at Tyr482 and Tyr470 in colon tumor samples." (PMID 24465712, 2014). "In conclusion, we have shown that pTyr421-cortactin is overexpressed in colon cancer, that curcumin modulates the activity of PTPN1 phosphatase to decrease cortactin phosphorylation and interaction with CTNND1, and ultimately to decrease colon cancer cell migration." (PMID 24465712, 2014).
colon carcinoma (continued). "Our data suggest potential usefulness of pTyr421 cortactin immunostaining as a biomarker of invasive colon cancer and provide further insight into the mechanism for chemopreventive effects of curcumin and its potential role in preventing metastatic colon cancer." (PMID 24465712, 2014). "It was shown that pTyr421-cortactin was up-regulated in colon cancer." (PMID 25566531, 2014). "However, in the tested tumor samples, PTPN1 expression was not affected, thus raising a possibility that relative PTPN1 deficiency should not be a factor limiting the efficacy of curcumin or other drugs targeting PTPN1/cortactin in potentially reducing colon cancer cell migration and metastasis." (PMID 24465712, 2014). "We entered the analyzed colon cancer marker gene set (CD2AP, GRB2, WASL, SRC, CTTN, CAPZA1, and Tks4) into this tool to elucidate which cancer hallmark-related pathways are influenced by these proteins." (PMID 39234565, 2024). "Immunohistochemical analysis of MYC, Cortactin, and ZEB1 also showed AXT suppresses metastasis of colon cancer cells into lung." (PMID 31263239, 2019). "Although the overexpression of cortactin in HCT116 cells was identified in previous studies, this report also showed that there is a high level of cortactin in colon cancer cell line HT29 as well." (PMID 26134506, 2015). "Altogether, Curcumin modulated the activity of PTPN1 phosphatase to reduce cortactin phosphorylation and interaction with CTNND1, and finally to reduce colon cancer cell migration." (PMID 25566531, 2014). "Although MTT did not reveal any significant changes in cell proliferation (data not shown), over-expression of cortactin isoform-a enhanced colorectral cancer cell migration and invasion in the three colon cancer cell lines." (PMID 28404950, 2017). "Our study indicated that knocking down PTBP1 or suppressing cortactin could both decrease cell migration and invasion in colon cancer cells and PTPB1 mediates inclusion of the alternative exon 11 in cortactin pre-RNA changing the F-actin binding domain involved in cell motility." (PMID 28404950, 2017). "Therefore, CBF is unlikely to strongly target cortactin in all colon cancer cells." (PMID 26134506, 2015). "Our data also supported the notion that over-expression of cortactin isoform-a could rescue the knocking down PTBP1 effect of migration and invasion in 3 colon cancer cell lines but not affect cell proliferation (data not shown)." (PMID 28404950, 2017). "Curcumin decreased the levels of pTyr421 cortactin in colon cancer cells in vitro by physically interacting with the non-receptor type 1 protein tyrosine phosphatase (PTPN1; PTP1b) to increase its activity, and dephosphorylate cortactin, thus reducing cancer cell migration." (PMID 24465712, 2014).
lung carcinoma (15 papers, 2011 to 2024). "Modulation of CTTN by microRNAs has been reported in association with several types of cancer, including in lung cancer via mi-R-182 and miR-509." (PMID 35562995, 2022). "miRNAs targeting the cortactin gene have been shown to inhibit invadopodial formation in human lung cancer, whereas its overexpression enhances cell migration in oral cancer." (PMID 33614634, 2020). "The fact prompted us to investigate the influence of cortactin on the malignant phenotypes in lung cancer cells." (PMID 29986736, 2018). "Data demonstrated that overexpression of miR-182 attenuated cortactin mRNA expression in lung cancer cells." (PMID 29986736, 2018). "In this report, we showed that miR-182 inhibited invadopodia formation in NSCLC by targeting CTTN and thus suppressing the migration and invasion of lung cancer cells." (PMID 29986736, 2018). "Our findings showed that miR-182 is a metastasis suppressor gene, and inhibited invadopodia formation and function, thus suppressing metastasis of lung cancer cells by targeting cortactin." (PMID 29986736, 2018). "Another report demonstrated that miR-182 suppressed cell proliferation of lung cancer cell line A549 in vitro and tumor growth in vivo through its interference with the target gene cortactin (CTTN) by epigenetic modification." (PMID 21920043, 2011). "Here we highlight a few recent topics related to CTTN expression and function in lung cancer." (PMID 35562995, 2022). "We observed in the experiment that the increased expression of p‐cortactin in lung cancer tissue may be due to the increased expression of cortactin, so we need more research to confirm the effect of CX3CL1 on the phosphorylation of cortactin in vivo." (PMID 33191645, 2021). "Among these proteins, we selected seven candidates (PC, keratin 18, heat shock 70 kDa protein-8, lectin galactoside-binding soluble 3 binding protein, DNA-dependent protein kinase catalytic subunit, plakophilin-3, cortactin) that have been known to participate in lung cancer progression." (PMID 34249688, 2021). "Furthermore, miR-182 negatively regulated invadopodia function, and suppressed extracellular matrix(ECM) degradation in lung cancer cells by inhibiting cortactin." (PMID 29986736, 2018). "Whether p300-mediated cortactin acetylation promoted by ING5 is involved in ING5-suppressed invasiveness of lung cancer cells deserves further validation." (PMID 29416718, 2018). "Therefore, in our study, we investigated the invasion of lung cancer through the assay of F-actin and cortactin to illustrate invadopodia formation in a 3D microfluidic matrix model." (PMID 23441195, 2013). "Therefore, in the next experiment, we will further investigate the regulation mechanism of the metastasis of lung cancer by verifying whether CX3CL1 regulates the phosphorylation of cortactin through MAPK/ERK and PI3K/AKT signalling pathways." (PMID 33191645, 2021). "We discovered that while Grb2 and cortactin are present to a lesser degree in the Tks4-formed complex, CD2AP and CAPZA1 are abundant in the tested three lung cancer cell lines." (PMID 38985526, 2024). "Results demonstrated that the high level of cortactin expression predicted a shorter PFS (log rank =8.201, P = 0.0042) and OS (log rank =6.225, P = 0.0126) in lung cancer patients." (PMID 29986736, 2018). "The results showed that cortactin expression was induced and peaked at 60–120 min after PDBu treatment, and peaked between h in the HGF-treated lung cancer cells." (PMID 29986736, 2018). "Collectively, our results demonstrated that miR-182 targeted CTTN gene in NSCLC and suppressed lung cancer invadopodia formation, and thus suppressed lung cancer metastasis." (PMID 29986736, 2018). "In summary, our results indicated that CX3CL1 furthered invasion and migration in lung cancer cells partly via activating cortactin, and CX3CL1 may be a potential molecule in regulating the migration and invasion of lung cancer." (PMID 33191645, 2021).
lung carcinoma (continued). "RNA expression data from these databases demonstrated that cortactin was expressed in lung cancer tissues 2.4-fold more than non-cancerous adjacent lung tissues." (PMID 29986736, 2018). "To determine whether PDBu or HGF could affect the cortactin expression, we tested cortactin expression and the cell migration and invasion ability in PDBu- or HGF-induced lung cancer cells." (PMID 29986736, 2018). "As we have illustrated, cortactin was overexpressed in human lung cancer tissues compared with matched adjacent non-tumor tissues." (PMID 29986736, 2018). "To investigate whether miR-182/CTTN is involved in regulating Rac1 and ROCK by modulating invadopodia formation in lung cancer cells, we measured the protein levels of Rac1 and Rock1." (PMID 29986736, 2018). "However, some studies recognized miR-182-5p as an inhibitor of the process of proliferation; indeed, miR-182-5p downregulates the mRNA products for proteins promoting the cancer development, including CTTN, RGS17, and CREB1 in ovarian papillary carcinoma, gastric adenocarcinoma, and in lung cancer." (PMID 36980984, 2023). "However, neither PDBu nor HGF upregulated N-WASP expression in CTTN-knockdown or miR-182 overexpressed lung cancer cells." (PMID 29986736, 2018). "Moreover, our results indicated that cortactin expression was upregulated when lung cancer cells were treated with PDBu or HGF, as well as invadopodia formation in non-small cell lung cancer cells, which indicated an important role of cortactin in invadopodia formation." (PMID 29986736, 2018).
head and neck squamous cell carcinoma (14 papers, 2008 to 2023). A squamous cell carcinoma that arises from any of the following anatomic sites: lip and oral cavity, nasal cavity, paranasal sinuses, pharynx, larynx, and salivary glands. "Overexpression of cortactin due to the amplification of the chromosome 11q13 locus has been observed in various cancers, such as head and neck squamous cell carcinoma, hepatocellular carcinoma, colon cancer, and bladder cancer." (PMID 37761244, 2023). "CTTN plays an important role in tumor progression in a number of malignancies, including esophageal carcinoma, hepatocellular carcinoma, and head and neck squamous cell carcinomas." (PMID 32120844, 2020). "Also, cortactin-related RhoA activity is documented to show cellular proliferation in head and neck squamous cell carcinoma." (PMID 33407452, 2021). "In this study, we sought to examine the prognostic importance of cortactin protein expression in head and neck squamous cell carcinoma (HNSCC)." (PMID 18268492, 2008). "In head and neck squamous cell carcinoma (HNSCC), CTTN induces gefitinib resistance by attenuating EGFR and c-MET degradation." (PMID 36831511, 2023). "CTTN is a known substrate of SRC and is reported to induce gefitinib resistance in head and neck squamous cell carcinoma (HNSCC)." (PMID 29556515, 2018). "Previously, CTTN has been identified as a bona fide oncogene located at 11q13 involved in ESCC carcinogenesis, contribute to the metastasis of various caners including ESCC, breast, hepatocellular, and head and neck squamous cell carcinomas." (PMID 22761904, 2012). "In head and neck squamous cell carcinoma cells, Coronin 1B, a coronin with significant homology to Coronin 1C, has been shown to regulate exosome secretion via destabilization of the actin network at MVB docking sites through interactions with cortactin and Rab27a71." (PMID 32686704, 2020).
gastric cancer (13 papers, 2011 to 2025). A primary or metastatic malignant neoplasm involving the stomach. "Cortactin overexpression has been linked to the promotion of carcinogenesis in various organs, including gastric cancer." (PMID 38646547, 2024). "Importantly, cortactin gene (cttn) amplification and protein overexpression are associated with carcinogenesis of various etiology, including gastric cancer." (PMID 38646547, 2024). "In conclusion, the diminished activation of both Src and Abl as well as the reduced phosphorylation of CagA point to cortactin as an interesting, potential new biomarker and therapeutic target for the prognosis and treatment of stomach cancer in the future." (PMID 34205064, 2021). "In gastric cancer cells, overexpressing CTTN resulted in an increased percentage of apoptosis, increased pro-apoptotic marker Bax, and decreased anti-apoptotic marker Bcl-2." (PMID 34831092, 2021). "The CTTN gene is amplified in many tumors including head and neck cancer, gastric cancer, and hepatocellular cancer." (PMID 27903975, 2017). "We therefore hypothesize that CagA disrupts gastric epithelial cell polarity by hijacking cortactin, and thus Par1b and ZO-1, suggesting a new signaling pathway for the development of gastric cancer by Helicobacter." (PMID 38646547, 2024). "Notably, injected CagA induces the overexpression of cortactin by a JNK-dependent pathway, suggesting a role in H. pylori-associated gastric cancer development." (PMID 38646547, 2024). "Therefore, it is remarkable that the phosphorylation level of intracellular CagA was dramatically reduced in the AGSΔcttn cells as observed in the present study, indicating that the importance of cortactin in the gastric cancer pathway." (PMID 34205064, 2021). "Cortactin can promote the proliferation of gastric cancer cells and EMT, while microRNA-545 (miR-545) can inhibit the expression levels of cortactin mRNA and protein in GC cells and has a negative regulatory effect on the carcinogenic activity of cortactin." (PMID 33195233, 2020). "Formation of the NEK9-ROBO1-SLIT2 ternary complex promoted NEK9-mediated phosphorylation of the transcriptional elongation factors, tripartite motif containing 28 (TRIM28) and cortactin (CTTN), which helped to promote metastasis in gastric cancer cells." (PMID 41154634, 2025). "Thus, the cortactin status could serve as a potential new biomarker of gastric cancer development." (PMID 34205064, 2021). "The impaired cell motility in cortactin knockdown gastric cancer cell lines, with a low cortactin phosphorylation level, can be rescued by the ectopic expression of wild-type cortactin, but not by the mutant cortactin (Y421/466/482F)." (PMID 22078467, 2011). "Notably, PLXDC2 was co‐localized with cortactin, suggesting that PLXDC2 might be involved in the formation of invasive protrusions together with cortactin, as previously reported in gastric cancer." (PMID 41365610, 2025). "Interestingly, it has also been reported that hyperphosphorylated cortactin might suppress cell migration by a negative feedback mechanism, as knockdown of cortactin in gastric cancer cells with high cortactin phosphorylation levels and high migratory potential further enhanced cell migration." (PMID 30976201, 2019).